ACBD5 (acyl-CoA binding domain containing 5)
Description:
Acyl-CoA binding protein which acts as the peroxisome receptor for pexophagy but is dispensable for aggrephagy and nonselective autophagy. Binds medium- and long-chain acyl-CoA esters.
Synonyms: KIAA1996; DKFZp434A2417; RDLKD
Tractability: Small molecule: a structure with a bound ligand is known. Antibody: UniProt predicts a signal peptide or a membrane-spanning region. PROTAC: ubiquitination databases record sites on it; its protein half-life has been measured.
Gene: Protein-coding gene on chromosome 10 (27,168,135 to 27,243,046, reverse strand). Ensembl gene ENSG00000107897.
Subcellular location: Peroxisome membrane
Subcellular location (Human Protein Atlas): Peroxisomes
Pathways (Reactome):
Signal Transduction: RHOA GTPase cycle; RHOC GTPase cycle
Metabolism: Peroxisomal lipid metabolism
Protein localization: Class I peroxisomal membrane protein import
Gene Ontology:
Molecular function: fatty-acyl-CoA binding
Biological process: pexophagy; fatty acid catabolic process; fatty acid metabolic process
Cellular component: membrane; peroxisome; cytoplasm; cytosol; peroxisomal membrane
Genetic constraint (gnomAD): Loss-of-function variants: 37 observed, 66.33 expected, observed/expected ratio (o/e) 0.56, 90% interval 0.43 to 0.73. The upper end of that interval is the gene's LOEUF score, 0.73, which puts it in group 3 of 6, group 1 being the genes least tolerant of losing a copy. Missense variants: 541 observed, 658.59 expected, observed/expected ratio (o/e) 0.82, 90% interval 0.76 to 0.88. Synonymous variants: 225 observed, 226.76 expected, observed/expected ratio (o/e) 0.99, 90% interval 0.89 to 1.11.
Gene-disease validity (ClinGen):
ClinGen rates the evidence that ACBD5 causes each of these diseases.
acyl-CoA binding domain containing protein 5 deficiency (autosomal recessive): Definitive. A disorder of a single peroxisomal protein, acyl-CoA binding domain containing protein 5, which forms a contact site between the peroxisomes and the ER.
Homologues: Orthologues: chimpanzee ACBD5 (99% identical), macaque ACBD5 (98% identical), dog ACBD5 (89% identical), rabbit ACBD5 (86% identical), pig ACBD5 (85% identical), mouse Acbd5 (80% identical), rat Acbd5 (80% identical), guinea pig ACBD5 (76% identical), rat AABR07046657.1 (74% identical), tropical clawed frog acbd5 (50% identical), zebrafish acbd5a (40% identical), zebrafish acbd5b (27% identical), and 3 more. Paralogues in human: ACBD4 (22% identical), ECI2 (13% identical), DBI (8% identical), ACBD7 (6% identical).
Diseases named in the same sentence as ACBD5 in open-access papers:
ACBD5 is named in the same sentence as 40 diseases in open-access papers, as found by Europe PMC text mining. Sharing a sentence is not in itself a finding about the gene and the disease. The quoted sentences say what the papers report.
Retinal dystrophy (5 papers, 2018 to 2025). Retinal dystrophy is an abnormality of the retina associated with a hereditary process. "Since the first ACBD5-deficient patient was identified in a genetic retinal dystrophy screen, its ocular pathology has received special attention and led to its OMIM name RDLKD." (PMID 41324649, 2025). "The first patients with a loss of ACBD5 function have recently been identified, suffering from retinal dystrophy and progressive leukodystrophy; ACBD5 deficiency leads to impaired peroxisomal β-oxidation of these very-long chain fatty acids (VLCFAs) and consequent accumulation." (PMID 32712071, 2020). "Mutations in ACBD5 show elevated levels of very long chain fatty acids and a defect in peroxisomal β-oxidation of very long chain fatty acids; patients with ACBD5 deficiency manifest with retinal dystrophy." (PMID 29859321, 2018). "Notably, early childhood retinal dystrophy paralleled by a nystagmus might be considered as a sign for further analyses toward mutations in ACBD5." (PMID 40672445, 2025). "Hence, further patient evaluations and future studies are needed to determine whether ACBD5-associated retinal dystrophy falls within the retinitis pigmentosa spectrum or represents a distinct pathological entity." (PMID 40672445, 2025). "Research indicates that mutations in the ACBD5 gene can lead to the accumulation of very long-chain fatty acids (VLCFA), which result in central nervous system (CNS) lesions, including severe leukodystrophy, retinal dystrophy, ataxia, and psychomotor delay." (PMID 40002775, 2025).
peroxisomal disorder (4 papers, 2020 to 2025). "The absence or dysfunction of the peroxisomal membrane protein Acyl-CoA Binding Domain-Containing Protein 5 (ACBD5) is the cause of the most recently discovered peroxisomal disorder “Retinal Dystrophy with Leukodystrophy” (RDLKD)." (PMID 40672445, 2025). "In ACBD5 KO HEK293 cells, we observed an increase in C26:0 and C26:0-lysoPC levels, which are changes commonly observed in peroxisomal disorders including ACBD5 deficiency." (PMID 37414147, 2023). "ACBD5 deficiency has recently been described as a new peroxisomal disorder characterized by the accumulation of VLCFA and neurological abnormalities (see Section 6)." (PMID 32044385, 2020). "ACBD5 deficiency is a novel peroxisome disorder with a largely uncharacterized pathology." (PMID 33244184, 2020).
leukodystrophy (3 papers, 2025). Leukodystrophies are a group of rare, progressive, metabolic, genetic diseases that affect the brain, spinal cord and often the peripheral nerves. "However, mutations in ACBD5 have been seen associated to leukodystrophy and pexophagy, having a possible effect on platelet formation and megakaryocyte differentiation." (PMID 40539042, 2025). "Although its relevance to ACBD5 deficiency remains to be established, current advances in the treatment options for leukodystrophies may also benefit the treatment of ACBD5 patients." (PMID 40672445, 2025).
X-linked adrenoleukodystrophy (3 papers, 2018 to 2020). X-linked adrenoleukodystrophy (X-ALD) is a peroxisomal disorder resulting in cerebral demyelination, axonal dysfunction in the spinal cord leading to spastic paraplegia, adrenal insufficiency and in some cases testicular insufficiency. "Peroxisomal single enzyme deficiencies include among others, acyl-CoA oxidase deficiency, ACBD5 deficiency, and the most common peroxisomal disorder, adrenoleukodystrophy (ALD)." (PMID 32903870, 2020). "PEDs affecting the β-oxidation of VLCFAs are X-linked adrenoleukodystrophy (ALD), ACOX1-, DBP-, and Acyl-CoA binding domain containing protein 5 (ACBD5) deficiency." (PMID 28849344, 2018).
Ataxia (2 papers, 2025). Ataxia refers to impaired coordination of voluntary muscle movement. "Evidence that ACBD5 plays important roles in the brain comes from Acbd5 knock-out mice, which display a progressive degeneration of the cerebellum, presenting as symptoms of ataxia such as kyphosis and unsteady gait." (PMID 40621503, 2025).
retinal degeneration (2 papers, 2020 to 2025). Degeneration of the retina. "To monitor a potential, progressive retinal degeneration we here analyzed retinae from cohorts of 3-month-old and 12-month-old Acbd5−/− mice." (PMID 41324649, 2025). "RDLKD patients lacking the peroxisomal membrane protein ACBD5 suffer from retinal degeneration described either as a cone-rod or rod-cone dystrophy." (PMID 41324649, 2025). "According to light microscopic histologic results, the retinal degeneration in Acbd5−/− mice is only moderate inducing no gross alterations in the retinal architecture." (PMID 41324649, 2025).
retinal dystrophy with leukodystrophy (2 papers, 2021 to 2025). Retinal dystrophy and leukodystrophy (RDLKD) is a peroxisomal enzyme deficiency caused by impaired very long chain fatty acid (VLCFA) metabolism. "ACBD5 deficiency, referred to in the OMIM database as “retinal dystrophy with Leukodystrophy” (RDLKD), is a rare congenital disorder caused by the absence of the peroxisomal membrane protein ACBD5." (PMID 40672445, 2025).
Alzheimer disease (1 paper, 2025). A progressive, neurodegenerative disease characterized by loss of function and death of nerve cells in several areas of the brain leading to loss of cognitive function such as memory and language. "Initial studies indicate that targeting peroxisomes could mitigate cognitive impairment and neurodegeneration in AD models, highlighting the potential of ACBD5 as a therapeutic target for Alzheimer’s disease." (PMID 40002775, 2025).
cerebellar degeneration (1 paper, 2025). Degeneration of the cerebellum. "Consistent with these motor deficits, both Acbd5–/– models show cerebellar degeneration marked by Purkinje cell loss, pronounced axonal swellings, and demyelination of cerebellar white matter tracts, which correlates with the cerebellar symptoms typically observed in RDLKD patients." (PMID 40672445, 2025). "Moreover, their ACBD5-deficient mice developed a significant gliosis throughout the white and gray matter of the telencephaolon, which correlates with the brain degeneration observed in RDLKD patients." (PMID 40672445, 2025).
epilepsy (1 paper, 2025). A brain disorder characterized by episodes of abnormally increased neuronal discharge resulting in transient episodes of sensory or motor neurological dysfunction, or psychic dysfunction. "Of note, many seizure-related genes identified in this study (for e.g. ACBD5, SLC6A5, STUB1) are not included in the routine epilepsy panel (R59) and this highlights the benefit of the gene-agnostic analytic approach offered by the rapid WES testing." (PMID 40399560, 2025).
glioma (1 paper, 2024). A benign or malignant brain and spinal cord tumor that arises from glial cells (astrocytes, oligodendrocytes, ependymal cells). "In summary, ATAD1_si3 and ACBD5_si3 transfection inhibited U251 cell proliferation, suggesting that ATAD1 and ACBD5 play an oncogenic role in glioma." (PMID 38406287, 2024). "Finally, CCK8 and flow cytometry were used to explore the biological function of ATAD1 and ACBD5 in glioma cells." (PMID 38406287, 2024).
HCMV infection (1 paper, 2022). "Our MCS-PRM showed that, by 48 h post-HCMV infection, the primary tethering partners ACBD5 and VAP-B are increased >threefold." (PMID 35953480, 2022). "During HCMV infection, ACBD5-mediated ER contacts with peroxisomes are suppressed early and increased late in infection to toggle the balance between peroxisome proliferation and membrane enlargement for the viral benefit." (PMID 35953480, 2022). "ER-peroxisome contacts, mediated by ACBD5, increase throughout HCMV infection for viral control of peroxisome size and numbers." (PMID 35953480, 2022). "For example, ER-peroxisome MCS proteins (ACBD5, ACBD4, VAP-A/B) were altered in a virus infection-specific manner, being increased during HCMV infection and decreased during Infl." (PMID 35953480, 2022). "During HCMV infection, we find that both PTPIP51 and ACBD5 increase in abundance, are enriched at MCSs, have elevated ER tethering, and are required for virus production." (PMID 35953480, 2022).
Huntington disease (1 paper, 2025). Huntington disease (HD) is a rare neurodegenerative disorder of the central nervous system characterized by unwanted choreatic movements, behavioral and psychiatric disturbances and dementia. "Additionally, the decreased ACBD5 expression level was associated with Huntington’s disease, while high GABARAPL1 and HSPA8 expression levels were concentrated in ECM receptor interaction." (PMID 40002775, 2025).
Macrothrombocytopenia (1 paper, 2017). "Finally, variants in the 5′ UTR of ANKRD26 (MIM: 610855) were reported to result in non-syndromic macrothrombocytopenia in 201121 after an initial erroneous report that variants in the neighboring gene ACBD5 (MIM: 616618) were responsible." (PMID 28669401, 2017).
metabolic syndrome (1 paper, 2021). A cluster of metabolic risk factors for CARDIOVASCULAR DISEASES and TYPE 2 DIABETES MELLITUS. "Additional dmCpG in regulatory regions of pathobiologically relevant genes included PA-dmCpG within the ACBD5 that is involved in long-chain FA metabolism; CD34, an adipocyte progenitor marker; and CDH18 that hosts variants associated with the metabolic syndrome." (PMID 34025721, 2021).
multiple sclerosis (1 paper, 2025). A progressive autoimmune disorder affecting the central nervous system resulting in demyelination. "For example, INL thickening has been associated with neuroinflammatory optic neuritis in multiple sclerosis, raising the question whether neuroinflammation may also account for the observed layer thickening in Acbd5−/− mice." (PMID 41324649, 2025).
Parkinson disease (1 paper, 2025). A progressive degenerative disorder of the central nervous system characterized by loss of dopamine producing neurons in the substantia nigra and the presence of Lewy bodies in the substantia nigra and locus coeruleus. "According to the GSEA results, the ACBD5, GABARAPL1, and HSPA8 were involved in five pathways, including proteasome, oxidative phosphorylation, citrate cycle TCA cycle, Parkinsons disease, and aminoacyl tRNA biosynthesis." (PMID 40002775, 2025).
cancer (2 papers, 2019 to 2024). A tumor composed of atypical neoplastic, often pleomorphic cells that invade other tissues. "Sustained proliferation is the most important characteristic of cancer cells, so the influence of ATAD1 and ACBD5 downregulation on A172 or U251 cell proliferation was assessed using a CCK8 assay." (PMID 38406287, 2024).
neurodegenerative disease (2 papers, 2021 to 2024). A disorder of the central nervous system characterized by gradual and progressive loss of neural tissue and neurologic function. "Although current knowledge of the phenotype associated with ACBD5 defects is limited to only four reported families, similar to ACBD6, individuals with defective ACBD5 seem to exhibit a neurodegenerative disease, albeit with a different range of associated symptoms." (PMID 37951597, 2024).
tumor (2 papers, 2020 to 2024). "The results showed that compared with normal tissues, the mRNA expression of five genes, ACBD5, ATAD1, DHRS4, GRHPR, and IDH1, was significantly up-regulated in tumor tissues." (PMID 38406287, 2024).
infection (1 paper, 2022). The state of being infected such as from the introduction of a foreign agent such as serum, vaccine, antigenic substance or organism. "Specifically, peroxisomes in ACBD5 KDs remain the same size and spherical shape throughout infection." (PMID 35953480, 2022). "This pointed to an anti-viral function for ACBD5 OE, a result we initially found puzzling as ACBD5 increases in abundance and tethering function during infection." (PMID 35953480, 2022). "Reconsidering our microscopy data, we noticed that ACBD5 OE prevented infection-induced peroxisome biogenesis, as cellular peroxisome numbers remained steady through 120 hpi in comparison to a five-fold increase in control cells." (PMID 35953480, 2022). "We optimized ACBD5 siRNA-mediated KDs and plasmid-based overexpressions (OEs) in fibroblasts, confirming expression throughout infection and low cytotoxicity." (PMID 35953480, 2022). "Given this role of ACBD5 in peroxisome restructuring during infection, we next tested its impact on virus production." (PMID 35953480, 2022). "Our findings that ACBD5 exerts an anti-viral effect on these tested infections raises the possibility of a role for ER-peroxisome MCSs in supporting virus production, which remains to be examined." (PMID 35953480, 2022). "As the ACBD5-VAPs complex regulates both peroxisome membrane growth and lipid metabolism, it is possible that ER-peroxisome contact contributes to the distinct peroxisome remodeling events observed during different infections." (PMID 35953480, 2022).
retinopathies (1 paper, 2025). "While patients with an ACBD5-deficiency show severe brain pathologies, all hitherto described patients also exhibit a prominent retinopathy, leading to an annotation “Retinal Dystrophy with Leukodystrophy” (RDLKD) in the OMIM database." (PMID 41324649, 2025). "Patients lacking the peroxisomal tail-anchored membrane protein ACBD5 (acyl-CoA binding domain-containing protein 5) have been first detected in a genome screen for uncharacterized retinopathies." (PMID 41324649, 2025).
ACBD5 also shares sentences with these, for which no sentence is quoted: adrenoleukodystrophy (2 papers); Aicardi-Goutières syndrome (1); amyotrophic lateral sclerosis (1); Atrophy (1); breast carcinoma (1); Cognitive impairment (1); lipid metabolic disorders (1); Nystagmus (1); optic neuritis (1); papillary thyroid cancer (1); peroxisomal biogenesis disorder (1); retinitis pigmentosa (1); Rod-cone dystrophy (1); salivary gland carcinoma (1); Spastic paraplegia (1); thyroid cancer (1); virus infection (1); Zellweger spectrum disorders (1).